IGSF8 (immunoglobulin superfamily member 8)
Description:
Member of the immunoglobulin superfamily (IgSF) that links tetraspanin-enriched microdomains to the actin cytoskeleton and plays several important roles in innate and adaptive immunity. Acts as an inducible receptor of HSPA8 on dendritic cells to enhance the CCL21/SLC-dependent migration of activated mature dendritic cells while attenuating their antigen-specific stimulatory capacities. In complex with alpha-actinins ACTN1 and ACTN4, regulates actin dynamics in the immune synapse and subsequent T-cell activation. Inhibits the entry of several viruses such as hepatitis C Virus (HCV) or HIV-1. Mechanistically, promotes a change in CD81 organization at the plasma membrane by significantly restricting its diffusion which in turn influences CD81 interaction with Claudin-1/CLDN1, preventing CLDN1 from acting as a co-receptor required for HCV entry. Accumulates at the presynaptic terminal, the producer cell side of the virological synapse, to prevent HIV-1 Env-mediated cell-cell fusion. Highly expressed on malignant cells with antigen presentation defects, interacts with NK receptor KIR3DL2 to suppress NK-cell cytotoxicity. May participate in the regulation of neurite outgrowth and maintenance of the neural network in the adult brain.
Synonyms: EWI-2; KCT-4; PGRL; CD316; CD81P3; EWI2; LIR-D1
Tractability: Antibody: UniProt places it where antibodies can reach, with high confidence; UniProt predicts a signal peptide or a membrane-spanning region; its Gene Ontology location is reachable by antibodies, with medium confidence. PROTAC: ubiquitination databases record sites on it; its protein half-life has been measured.
Gene: Protein-coding gene on chromosome 1 (160,091,340 to 160,101,109, reverse strand). Ensembl gene ENSG00000162729.
Subcellular location: Cell membrane
Subcellular location (Human Protein Atlas): Vesicles
Gene Ontology:
Molecular function: protein binding; signaling receptor activity
Biological process: positive regulation of cell migration; cell motility; nervous system development; single fertilization; skeletal muscle tissue development; regulation of cell motility
Cellular component: extracellular exosome; membrane; plasma membrane; hippocampal mossy fiber to CA3 synapse; presynaptic membrane
Genetic constraint (gnomAD): Loss-of-function variants: 44 observed, 54.92 expected, observed/expected ratio (o/e) 0.8, 90% interval 0.63 to 1.03. The upper end of that interval is the gene's LOEUF score, 1.03, which puts it in group 4 of 6, group 1 being the genes least tolerant of losing a copy. Missense variants: 726 observed, 844.47 expected, observed/expected ratio (o/e) 0.86, 90% interval 0.81 to 0.91. Synonymous variants: 310 observed, 355.6 expected, observed/expected ratio (o/e) 0.87, 90% interval 0.79 to 0.96.
Homologues: Orthologues: chimpanzee IGSF8 (100% identical), macaque IGSF8 (94% identical), rabbit IGSF8 (94% identical), pig IGSF8 (91% identical), dog IGSF8 (90% identical), rat Igsf8 (88% identical), mouse Igsf8 (88% identical), guinea pig IGSF8 (85% identical), tropical clawed frog XB5942349 (47% identical), zebrafish igsf8 (37% identical). Paralogues in human: IGSF3 (29% identical), CD101 (29% identical), PTGFRN (25% identical), VSTM4 (8% identical), VSTM2A (8% identical).